TMEM26 (transmembrane protein 26)
Synonyms: MGC35010; Em:AC068892.1
Tractability: Antibody: UniProt predicts a signal peptide or a membrane-spanning region.
Gene: Protein-coding gene on chromosome 10 (61,406,642 to 61,453,381, reverse strand). Ensembl gene ENSG00000196932.
Subcellular location: Membrane
Gene Ontology:
Cellular component: membrane
Genetic constraint (gnomAD): Loss-of-function variants: 27 observed, 22.05 expected, observed/expected ratio (o/e) 1.22, 90% interval 0.9 to 1.68. The upper end of that interval is the gene's LOEUF score, 1.68, which puts it in group 6 of 6, group 1 being the genes least tolerant of losing a copy. Missense variants: 478 observed, 436.71 expected, observed/expected ratio (o/e) 1.09, 90% interval 1.01 to 1.18. Synonymous variants: 212 observed, 180.99 expected, observed/expected ratio (o/e) 1.17, 90% interval 1.05 to 1.31.
Homologues: Orthologues: macaque TMEM26 (95% identical), chimpanzee TMEM26 (86% identical), pig TMEM26 (84% identical), dog TMEM26 (81% identical), rabbit TMEM26 (81% identical), rat Tmem26 (70% identical), mouse Tmem26 (69% identical), tropical clawed frog tmem26 (60% identical), guinea pig TMEM26 (53% identical), zebrafish tmem26a (45% identical), zebrafish tmem26b (41% identical), Drosophila melanogaster CG14238 (32% identical), and 1 more.
Diseases named in the same sentence as TMEM26 in open-access papers:
TMEM26 is named in the same sentence as 13 diseases in open-access papers, as found by Europe PMC text mining. Sharing a sentence is not in itself a finding about the gene and the disease. The quoted sentences say what the papers report.
breast carcinoma (4 papers, 2016 to 2022). "The notion that ERα activity is linked to TMEM26 protein expression is supported by data obtained by immunohistochemical analysis of 207 breast cancer specimens showing a statistically highly significant association between the status of ERα and PR and the status of TMEM26." (PMID 27224909, 2016). "We next sought to analyze whether the differences in TMEM26 protein expression patterns as observed between breast cancer cell lines may be associated with differences in the activities of certain signaling pathways or with differences in the expression of specific proteins." (PMID 27224909, 2016). "Our data, therefore, show that both NIC and Pal either alone or in combination significantly increase MCSC population, anti-inflammatory cytokines, and key browning marker TMEM26 in HCC70 breast cancer cells." (PMID 33414685, 2020). "Here, we show that TMEM26 is also an N-glycosylated protein in breast cancer cells and that N-glycosylation is important for its retention at the plasma membrane." (PMID 27224909, 2016). "To test if TMEM26 is also N-glycosylated in breast cancer cells, we treated MCF-7 cell protein extracts with N-glycosylase (PNGase F) alone or with a mixture of PNGase F, O-glycosylase and sialidase." (PMID 27224909, 2016). "In summary, our data suggest that, in breast cancer cells, TMEM26 is an ERα-regulated N-glycosylated protein whose function at the cell surface is to control integrin β1 function." (PMID 27224909, 2016). "Data obtained by spheroid formation assays confirmed that TMEM26 and integrin β1 can have opposite effects in breast cancer cells." (PMID 27224909, 2016). "Here, we studied TMEM26 RNA and protein expression in breast cancer cell lines, examined TMEM26 protein expression in breast cancer samples and analyzed its potential importance for endocrine resistance." (PMID 27224909, 2016). "In primary breast cancer, TMEM26 protein expression was higher in ERα (estrogen receptor α)/PR (progesterone receptor)-positive cancers." (PMID 27224909, 2016). "The finding that desensitization of ERα-positive breast cancer cells to the anti-estrogen fulvestrant was accompanied by a decline in TMEM26 RNA expression prompted us to compare TMEM26 expression in ERα-dependent and ERα-independent breast cancer cell lines." (PMID 27224909, 2016). "As was found by immunocytochemical analysis of breast cancer cell lines, TMEM26 specific-immunoreactivity was found in the cytoplasm, but not in the nucleus of the tumor cells." (PMID 27224909, 2016). "For the analysis of TMEM26 protein expression in fulvestrant-resistant breast cancer cell lines, cells were grown in fulvestrant-free medium for two weeks before proteins were extracted to avoid direct influence of fulvestrant on TMEM26 expression." (PMID 27224909, 2016). "Collectively, these data show that TMEM26 is also N-glycosylated in breast cancer cells and further suggest that p53TMEM26 and p44TMEM26 are N-glycosylated derivatives of p40TMEM26." (PMID 27224909, 2016). "TMEM26 is also a transmembrane protein that may act as a tumor suppressor by impeding the acquisition of endocrine resistance in breast cancer." (PMID 35860577, 2022). "We next examined the TMEM26 protein status in 207 breast cancer specimens by immunohistochemistry." (PMID 27224909, 2016). "Based on this assumption and given the likelyhood that ERα positively regulates p53TMEM26 expression as suggested by the data obtained by fulvestrant, it makes sense that TMEM26-specific immunoreactivity in breast cancer specimens correlates with ERα- and PR-positivity." (PMID 27224909, 2016). "Also, TMEM26 expression was significantly higher in post-menopausal as compared to pre-menopausal breast cancer patients." (PMID 27224909, 2016).
breast carcinoma (continued). "On the other hand, TMEM26 is also expressed in ERα-negative breast cancer, where a high TMEM26-specific immunoreactivity is significantly associated with unfavorable survival, suggesting different functions of TMEM26 in ERα-positive and -negative breast cancers." (PMID 27224909, 2016). "We have previously shown that stromal cells desensitize breast cancer cells to the anti-estrogen fulvestrant and, along with it, downregulate the expression of TMEM26 (transmembrane protein 26)." (PMID 27224909, 2016). "The finding that stromal cell-induced fulvestrant resistance was accompanied by changes in TMEM26 expression prompted us to study TMEM26 expression in fulvestrant-treated MCF-7 cells and in fulvestrant-resistant MCF-7 and T47D breast cancer cell lines." (PMID 27224909, 2016). "In addition, nicotine or nicotine plus HFD increased a subset of mammary cancer stem cells (MCSCs) and key adipose browning markers CD137 and TMEM26." (PMID 33414685, 2020). "Moreover, SCUBE2, TMEM26, and SMOC2 were validated as subtype-specific coding genes in luminal A breast cancer, CDK12 and SDC1 in HER2 breast cancer and PSAT1 in triple negative breast cancer in TCGA and GEO datasets." (PMID 31801944, 2019). "Collectively, these data demonstrate that TMEM26 and integrin β1 have opposing effect on 3D cell aggregation by ERα-positive and -negative breast cancer cells." (PMID 27224909, 2016). "On the other hand, high TMEM26-specific immunoreactivity correlated significantly with a unfavorable outcome of patients diagnosed with ERα-negative (triple-negative) breast cancer." (PMID 27224909, 2016). "It is possible that the number of breast cancer cell lines we have studied was not high enough to confirm this connection between ERα and TMEM26 protein expression also with cultured cells." (PMID 27224909, 2016). "While ERα-positive breast cancer cell lines showed higher TMEM26 RNA levels than ERα-negative ones, there seemed to be no obvious association of the expression of any of the TMEM26 protein isoforms with the ERα status in Western blot analysis." (PMID 27224909, 2016). "In an effort to study the function and regulation of TMEM26 in breast cancer cells, we found that breast cancer cells express non-glycosylated and N-glycosylated isoforms of the TMEM26 protein and demonstrate that N-glycosylation is important for its retention at the plasma membrane." (PMID 27224909, 2016). "Collectively, these data show that, in ERα-positive breast cancer, the TMEM26 protein is not an indicator for survival, though it may have a potential predictive value for patients treated with an aromatase inhibitor." (PMID 27224909, 2016). "Measurements of the TMEM26 RNA levels in three ERα-positive (MCF-7, T47D and BT474) and three ERα-negative breast cancer cell lines (SKBR3, MDA-MB-231 and BT20) revealed that TMEM26 RNA levels are significantly higher in the ERα-positive breast cancer cell lines." (PMID 27224909, 2016). "This pathway may be particularly important for TMEM26 protein expression in ERα-negative breast cancers, such as the triple-negative breast cancers, which show the highest activity of the PI3K/AKT pathway among all breast cancers." (PMID 27224909, 2016).
breast tumors (3 papers, 2014 to 2025). "In our research, expression of marker genes of fat browning, like UCP1, PRDM16, CIDEA, COX7A1, PGC1α, TMEM26 and TBX1, was up-regulated in adipose tissue adjacent to breast tumors." (PMID 25291184, 2014).
adrenal tumors (1 paper, 2022). "They assessed in the perirenal region of PPGL higher expression of UCP1, CIDEA, ELOVL3, EBF3, FBXO31 and LHX8, but not TNFSRF9, TBX1 or TMEM26, in comparison with seven subjects with non-functional adrenal tumors." (PMID 35327387, 2022).
Cachexia (1 paper, 2018). Severe weight loss, wasting of muscle, loss of appetite, and general debility related to a chronic disease. "Interestingly, beige fat-associated genes (Tmem26 and Tbx1) but not brown fat-associated genes (Eva1 and Pdk4) were upregulated in patients with late-stage cachexia." (PMID 29338749, 2018).
diabetes (1 paper, 2021). "Chronic training increased the mRNA level of PGC-1α of SAT by 1.2-fold and 1.6-fold in the control group and the pre-diabetes group, respectively, whereas no significant changes neither in the brown-fat-selective gene Prdm16 or other known browning genes TBX1, TMEM26, and CD137 for both groups." (PMID 33922998, 2021).
cancer (4 papers, 2012 to 2023). A tumor composed of atypical neoplastic, often pleomorphic cells that invade other tissues. "•The involvement of TMEM26, a novel plasma membrane protein, in cancer EMT was examined for the first time." (PMID 37611445, 2023). "The Ucp1 mRNA levels were lower in cancer patients vs. controls (p = 0.01), whereas Cidea and Tmem26 mRNA levels were higher in cancer patients." (PMID 35454855, 2022). "In contrast, in ERα-negative cancer, specifically in triple-negative cancer, high TMEM26 is associated with a higher risk of recurrence." (PMID 27224909, 2016). "The remaining other 4 genes, VAX1 KCNV1, ECEL1 and TMEM26, were found in the present study to be hypermethylated in BC, but there were no any background record that provided mechanisms in the carcinogenesis and development of any cancer, let alone BC." (PMID 22529986, 2012). "In our analyses, Cidea and Tmem26 mRNA levels and PGC1α protein levels were increased in the SAT of cancer patients with respect to controls, whereas Pdk4 expression was only slightly increased with respect to controls." (PMID 35454855, 2022).
tumor (4 papers, 2012 to 2023). "Evidently, the tumor tissues exhibited higher staining and contained a higher number of TMEM26-positive cells by quantification." (PMID 37611445, 2023). "For the group of patients diagnosed with an ERα-negative tumor (N = 56), high tumoral TMEM26 expression was found to be significantly associated with a higher risk of recurrence (~2.4-fold, p = 0.049)." (PMID 27224909, 2016). "Within this group, patients diagnosed with a triple-negative tumor (N = 30, p = 0.043), but not with a Her2-positive tumor (N = 49) showed a higher risk for recurrence at high tumoral TMEM26 expression." (PMID 27224909, 2016). "The methylation status of ECEL1 and TMEM26 was significantly related to a high degree of tumor differentiation, with HR = 2.43 (95% CI, 1.19 to 4.97; P = 0.01) and 2.32 (95% CI, 1.11 to 4.85; P = 0.03), respectively, suggesting that they are involved in BC malignancy and progression." (PMID 22529986, 2012). "By examining TMEM26 in the ESCC and para-tumor control tissues, TMEM26 expression was elevated in the ESCC tumor." (PMID 37611445, 2023). "Hence, by inhibiting integrin β1, TMEM26 may be a potential tumor suppressor." (PMID 27224909, 2016). "Also patients who were diagnosed with an ERα-negative tumor and who received chemotherapy showed a more unfavorable recurrence-free survival (p < 0.0001) at high tumoral TMEM26 expression." (PMID 27224909, 2016).
TMEM26 also shares sentences with these, for which no sentence is quoted: triple-negative breast carcinoma (2 papers); esophageal squamous cell carcinoma (1); glioma (1); Hepatic steatosis (1); infection (1); Obesity (1).